THPO (thrombopoietin)
Diseases named in the same sentence as THPO in open-access papers (continued):
Sharing a sentence is not in itself a finding about the gene and the disease.
diabetes (7 papers, 2014 to 2022). "Thrombopoietin levels were inversely associated with platelet turnover parameters and were significantly increased in patients with diabetes and in smokers." (PMID 24465602, 2014). "In conclusion, our results suggest that increased THPO levels may enhance platelet activation in patients with type 1 diabetes mellitus and contribute to increased cardiovascular risk in this patient population." (PMID 34210000, 2021). "Diabetes caused an increase in circulating thrombopoietin (TPO), in the observation of TPO expression analyzing the ELISA measurement, it was found that daily oral with various concentration of triterpenes was exactly able to reduce the concentration of serum TPO from circulation system." (PMID 27378920, 2016). "The platelet count below the reference value, already observed in our previous study, can be explained by reduced thrombopoietin production due to the liver and kidney damage associated with STZ-induced diabetes." (PMID 36395179, 2022). "In the present study, thrombopoietin levels were significantly increased in patients with diabetes, which is in accordance with previous results from our group." (PMID 24465602, 2014). "Thrombopoietin levels were significantly increased in patients with diabetes (median pg/mL [IQR]: 50 vs. 43, p = 0.03), smokers (51 vs. 43, p = 0.003) and in patients without a history of myocardial infarction (53 vs. 43, p = 0.03)." (PMID 24465602, 2014). "The results of our study suggest that THPO may participate in the pathophysiology of enhanced platelet activation in patients with type 1 diabetes mellitus." (PMID 34210000, 2021). "Moreover, thrombopoietin levels were significantly increased in patients with diabetes (p = 0.03) and in smokers (p = 0.003)." (PMID 24465602, 2014). "Furthermore, thrombopoietin was significantly increased in patients with diabetes and in smokers." (PMID 24465602, 2014). "Furthermore, thrombopoietin levels were increased in patients with diabetes and in smokers." (PMID 24465602, 2014). "Multivariate joint model results suggested that interleukin-6 had the strongest effect on patient survival, whereas the platelet count was marginal; thrombopoietin and diabetes had no clinically relevant effect, similar to those observed in univariate models." (PMID 35071777, 2022). "Thrombopoietin and diabetes did not affect the survival of patients in any of the univariate models." (PMID 35071777, 2022). "To date, there had been no reports that focused on the anti-THPO antibody in patients with type 2 diabetes mellitus (T2DM)." (PMID 32260359, 2020).
liver dysfunction (7 papers, 2015 to 2025). "Moreover, liver dysfunction, which is common in critically ill patients, can impair platelet production, as the liver plays a crucial role in synthesizing thrombopoietin, a hormone essential for platelet formation." (PMID 40407554, 2025). "In addition to rebalanced coagulation there is altered platelet production due to decreased thrombopoietin production by liver, increased von Willebrand factor from low grade endothelial cell activation, and hyperfibrinolysis and dysfibrinogenemia from altered synthetic liver dysfunction." (PMID 33425821, 2020).
myeloproliferative neoplasm (7 papers, 2018 to 2024). A clonal hematopoietic stem cell disorder, characterized by proliferation in the bone marrow of one or more of the myeloid (i.e., granulocytic, erythroid, megakaryocytic, and mast cell) lineages. "Murine bone marrow cells expressing ectopic THPO caused a fatal, transplantable myeloproliferative disorder with splenomegaly, osteomyelofibrosis, pancytopenia, and leukemic transformation." (PMID 33777803, 2021). "Similarly, a transient myeloproliferative disorder resembling chronic myeloid leukemia (CML) has been described in an infant with an inherited THPO mutation." (PMID 33712866, 2021). "Here, we investigated EPO and thrombopoietin (TPO) induced SOCE and PLCγ1 activation in hematopoietic cells exhibiting activating mutations in JAK2 and CALR which are disease-initiating events in myeloproliferative neoplasms (MPNs)." (PMID 38509561, 2024).
essential thrombocythemia (6 papers, 2011 to 2021). A chronic myeloproliferative neoplasm that involves primarily the megakaryocytic lineage. "Hereditary forms of primary thrombocytosis are caused by germline mutations within the genes encoding thrombopoietin (THPO), its receptor (MPL), and the receptor’s effector kinase Januskinase2 (JAK2)." (PMID 33712866, 2021). "Clinically, hereditary primary thrombocytosis based on THPO germline mutations has been described to be associated with vasomotor, hemorrhagic, and thrombotic symptoms." (PMID 33712866, 2021). "Platelet production is usually dependent on thrombopoietin; however, it can be thrombopoietin-independent in haemopoietic neoplasia affecting megakaryocytes, e.g., essential thrombocythemia." (PMID 31991713, 2020). "In another case, one base deletion in 5′UTR of thrombopoietin (TPO) gene is shown to elevate the serum TPO levels leading to familial essential thrombocythemia." (PMID 22145020, 2011).
iron deficiency (5 papers, 2008 to 2025). "In patients with inflammation-associated iron deficiency, the release of cytokines such as interleukin-6 and thrombopoietin further stimulate platelet production." (PMID 41463898, 2025). "Of particular significance, dogs with iron deficiency had higher erythropoietin and lower thrombopoietin concentrations than dogs with normal serum iron." (PMID 41463898, 2025). "The high platelet count is likely due to increased thrombopoiesis, which is induced by higher plasma levels of thrombopoietin and IL-6 or is caused by iron deficiency." (PMID 36984554, 2023).
myelodysplastic syndrome (5 papers, 2015 to 2024). A clonal hematopoietic disorder characterized by dysplasia and ineffective hematopoiesis in one or more of the hematopoietic cell lines. "A promising example of this synergistic approach comes from a recent phase II study, which combined 5-azacytidine with the thrombopoietin mimetic romiplostim in patients with myelodysplastic syndrome (MDS), showing positive outcomes." (PMID 39519209, 2024). "The effect of recombinant human thrombopoietin (rhTPO) is largely unknown in lower-risk myelodysplastic syndrome (LR-MDS)." (PMID 34778037, 2021). "This study aimed to explore the effects of recombinant human thrombopoietin (rhTPO) on platelet recovery in decitabine, cytarabine, aclarubicin, and G-CSF (DCAG)-treated patients with intermediate-high-risk myelodysplastic syndrome/hypo proliferative acute myeloid leukemia." (PMID 37000082, 2023). "Recombinant human thrombopoietin (rhTPO) administration has been demonstrated to increase platelet count in patients with immune thrombocytopenia, chemotherapy-induced thrombocytopenia, myelodysplastic syndromes (MDS), and platelet apheresis donors." (PMID 25861635, 2015).
colorectal cancer (4 papers, 2014 to 2023). A primary or metastatic malignant neoplasm that affects the colon or rectum. "As evidenced in colorectal cancer, colorectal cancer cells secreted IL‐6, and stimulated platelet production by increasing thrombopoietin secretion." (PMID 37807972, 2023). "In colorectal cancer, thrombopoietin (TPO) was known to promote self-renewal and metastasis of CD110+ tumor-initiating cells (TICs) to the liver by activating lysine degradation." (PMID 35752862, 2022).
deep vein thrombosis (4 papers, 2017 to 2024). "IL-6 was reported to contribute to deep vein thrombosis via induction of hepatic thrombopoietin and dysregulation of miR-338–5p expression." (PMID 35203844, 2022).
dengue (4 papers, 2016 to 2020). "For example, in culture of HepG2 cells the trombinol, a bioactive fraction of Psidium guajava, induced the thrombopoietin production, and the authors postulate that this production could be considered as an alternative treatment in patients infected with dengue." (PMID 31694638, 2019).
neutropenia (4 papers, 2013 to 2025). A decrease in the number of neutrophils found in the blood. "Since JAK2 is downstream of erythropoietin (EPO), granulocyte-macrophage colony-stimulating factor (GM-CSF), and thrombopoietin (TPO), neutropenia has been found in clinical trials with the JAK inhibitors baricitinib and tofacitinib both of which target JAK2 to some extent." (PMID 33343569, 2020).
acute coronary syndrome (3 papers, 2014 to 2021). Signs and symptoms related to acute ischemia of the myocardium secondary to coronary artery disease. "Elevated plasma THPO levels have been reported in patients with acute coronary syndromes." (PMID 34680994, 2021). "This may offer an explanation for the contrasting results, since the interaction between thrombopoietin and thrombopoiesis may be altered during acute coronary syndrome." (PMID 24465602, 2014).
acute myeloid leukemia (3 papers, 2015 to 2023). Acute myeloid leukemia (AML) is a group of neoplasms arising from precursor cells committed to the myeloid cell-line differentiation. "Previous studies have demonstrated that the small molecule thrombopoietin (TPO) mimetic, eltrombopag (E), induces apoptosis in acute myeloid leukemia (AML) cells." (PMID 25915523, 2015).
autoimmune disease (3 papers, 2018 to 2024). A disorder resulting from loss of function or tissue destruction of an organ or multiple organs, arising from humoral or cellular immune responses of the individual to their own tissue constituents. "Immune thrombocytopenia (ITP) is a common acquired autoimmune disease, and thrombopoietin (TPO) is an important cytokine that regulates the production of megakaryocytes and platelets." (PMID 30224899, 2018).
chronic viral hepatitis (3 papers, 2013 to 2024). "In conclusion, the mechanisms involved in viral hepatitis-associated ITP are complex, and diagnosis should be clarified clinically with the aid of antiplatelet antibodies, thrombopoietin, and viral serology tests." (PMID 37635907, 2023).
Hepatitis (3 papers, 2015 to 2024). Inflammation of the liver. "This has a pathophysiological basis as platelet synthesis is regulated by thrombopoietin, a glycoprotein hormone synthesized in the liver and an inverse correlation has been reported between the degree of hepatitis and the platelet count." (PMID 38330228, 2024). "In addition to elevation of cytokine levels, thrombopoietin might also have contributed the increase of MPV in our patients with hepatitis A." (PMID 27716426, 2016).
leukemia (3 papers, 2021 to 2022). A malignant (clonal) hematologic disorder, involving hematopoietic stem cells and characterized by the presence of primitive or atypical myeloid or lymphoid cells in the bone marrow and the blood. "Our recent prospective phase II single-arm study has revealed that combination regimen of granulocyte colony-stimulating factor (G-CSF) and recombinant human thrombopoietin (rhTPO) could improve the curative effect on elderly patients with leukemia, yet the precise mechanism remains unknown." (PMID 35768562, 2022).
myocardial infarction (3 papers, 2014 to 2025). Gross necrosis of the myocardium, as a result of interruption of the blood supply to the area, as in coronary thrombosis. "Infusing platelets and using thrombopoietin may lead to stent thrombosis, acute myocardial infarction, and cerebral infarction, as seen in our second patient who developed a life-threatening massive cerebral infarction after thrombopoietin therapy." (PMID 41341297, 2025). "Thus, we evaluated associations between six novel markers (E-Selectin, P-Selectin, thrombomodulin, thrombopoietin, intercellular adhesion molecule 3 and GPIIb/IIIa) and established cardiovascular risk factors as well as the risk of myocardial infarction (MI) in a population-based study." (PMID 30816120, 2019).
osteomyelofibrosis (3 papers, 2020 to 2021). "Primary myelofibrosis is a condition associated with somaticmutations in JAK2 or other factors that activate the thrombopoietin signalingpathway." (PMID 32303876, 2020). "Spleen weight was also reduced in these mice after 33 weeks and, most importantly, there was complete reversal of the osteomyelofibrosis and splenic EMH associated with JAK2V617F expression, while plasma THPO was markedly elevated." (PMID 32479500, 2020). "Splenomegaly developed after 33 weeks of age, along with osteomyelofibrosis and splenic EMH, while plasma THPO was reduced relative to the wild-type mouse, indicating increased THPO utilization." (PMID 32479500, 2020).
acute liver failure (2 papers, 2022 to 2026). Rapid deterioration of liver function causing encephalopathy and coagulopathy. "The aim of this study is to investigate the effect of recombinant human thrombopoietin (rhTPO) on liver regeneration in rats with acute liver failure (ALF) induced by D-galactosamine (D-GalN)." (PMID 41601961, 2026).
bone marrow failure (2 papers, 2018 to 2024). "Recognizing patients with THPO mutations among those with juvenile bone marrow failure is essential to provide them with appropriate substitutive therapy and prevent the use of invasive and unnecessary treatments, such as hematopoietic stem cell transplantation or immunosuppression." (PMID 29191945, 2018).
chronic myeloid leukemia (2 papers, 2015 to 2016). "CRKL has a role in platelet aggregation through inducing tyrosine phosphorylated via thrombopoietin in both chronic myeloid leukemia patients’ and upregulated in myocardial infraction patients’ platelets." (PMID 27336623, 2016).
endothelial dysfunction (2 papers, 2017 to 2024). In vascular diseases, endothelial dysfunction is a systemic pathological state of the endothelium (the inner lining of blood vessels) and can be broadly defined as an imbalance between vasodilating and vasoconstricting substances produced by (or acting on) the endothelium. "However, in our study the role of thrombopoietin in endothelial dysfunction seems rather neglectable." (PMID 28918499, 2017). "Fourth, there is a limitation to explaining the mechanism of an independent role of platelets in microvascular endothelial dysfunction due to a lack of data about thrombopoietin, C-reactive protein, pro-inflammatory cytokines, renin, angiotensin II, or aldosterone in this study." (PMID 38248790, 2024).
familial thrombocytosis (2 papers, 2025). Familial thrombocytosis is a type of thrombocytosis, a sustained elevation of platelet numbers, which affects the platelet/megakaryocyte lineage and may create a tendency for thrombosis and hemorrhage but does not cause myeloproliferation. "Familial thrombocytosis (FT) is a rare autosomal-dominant disorder, primarily caused by activating mutations in the thrombopoietin (THPO) gene and germline mutations in the myeloproliferative leukemia (MPL) virus oncogene." (PMID 40507313, 2025).
hepatocellular carcinoma (2 papers, 2021). A malignant tumor that arises from hepatocytes. "For example, a recent report suggests that in hepatocellular carcinoma, THPO may facilitate tumor progression by promoting VEGF signaling in hepatocytes." (PMID 34463253, 2021).
Hyperglycemia (2 papers, 2022 to 2024). An increased concentration of glucose in the blood. "Hyperglycemia leads to the synthesis of thrombopoietin in the liver through its action on the Receptor for Advanced Glycation End (RAGE) products." (PMID 35710773, 2022). "Moreover, hyperglycemia increases thrombopoietin production by neutrophils in the liver through the receptor for advanced glycation end products; these processes can lead to an increase in platelet size." (PMID 38431644, 2024).
lung carcinoma (2 papers, 2023 to 2025). "In conclusion, our results suggest that MCs may contribute to lung cancer-related thrombosis through the release of cytokines, including IL-13, SerpinE1, and Thrombopoietin, following the uptake of lung cancer cell-derived exosomes." (PMID 37143160, 2023).
malnutrition (2 papers, 2013 to 2019). Inadequate nutrition resulting from poor diet, malabsorption, or abnormal nutrient distribution. "Also, it could be possibly be as a result of malnutrition during Ramadan Fasting which may directly affect marrow processes of thrombopoiesis or indirectly affect this phenomenon by reducing thrombopoietin and other growth factors generally involved in hemopoiesis." (PMID 24570826, 2013).
myeloid neoplasm (2 papers, 2021 to 2022). Proliferation of myeloid cells originating from a primitive stem cell. "Here, we propose a monoallelic deletion in THPO as a possible candidate variant of germline predisposition to myeloid malignancies." (PMID 36534659, 2022). "However, the THPO variant identified in this study has not been shown to underlie the predisposition to myeloid malignancy yet." (PMID 36534659, 2022).
Obesity (2 papers, 2023). Accumulation of substantial excess body fat. "Another factor contributing to platelet production is thrombopoietin, which is higher in obesity, at least in women." (PMID 36814334, 2023).
Polycythemia vera (2 papers, 2020 to 2026). "The patient exhibited an unprecedented 80% allele frequency of JAK2 V617F, significantly exceeding the average 30 to 50% observed in typical polycythemia vera cases, which led to abnormal enhancement of thrombopoietin signaling and megakaryocyte proliferation." (PMID 41560006, 2026). "Most importantly, elimination of thrombopoietin gene expression abrogated the polycythemia vera phenotype in this JAK2V617F transgenic mouse model, which could be completely restored by expression of a single thrombopoietin allele." (PMID 32479500, 2020).
preeclampsia (2 papers, 2014 to 2023). Preeclampsia is a hypertensive disorder of pregnancy that is characterized by new-onset hypertension with proteinuria presenting after 20 weeks of gestation, and depending on mild or severe forms may initially present with severe headache, visual disturbances, and hyperreflexia. "The platelet activation in PE is related to the alternation of the coagulation process between platelets and endothelial cells, thrombopoietin increases in patients with preeclampsia, so MPV and PDW are increased in preeclampsia more than in normal pregnant women." (PMID 37904105, 2023). "The role of GnRH signal, B cell receptor signal, and thrombopoietin signal in preeclampsia is still unknown." (PMID 25392996, 2014).
systemic lupus erythematosus (2 papers, 2020). An autoimmune multi-organ disease typically associated with vasculopathy and autoantibody production. "While it was unexpected to detect the regulation of a protein involved in megakaryocyte maturation, thrombopoietin has previously been shown to be elevated in systemic lupus erythematosus and where it was strongly correlated with and likely induced by CCL3." (PMID 33246483, 2020).
type 2 diabetes (2 papers, 2019 to 2020). "No studies on ICAM3, thrombopoietin, and GP IIb/IIIa in relation to type 2 diabetes risk were found." (PMID 31783601, 2019).
acquired aplastic anemia (1 paper, 2023). Acquired aplastic anemia is a rare, serious blood disorder, due to failure of the bone marrow to produce blood cells. "Romiplostim, a thrombopoietin (TPO) receptor antagonist, promotes tri-lineage hematopoiesis in patients with acquired aplastic anemia (AA)." (PMID 37206485, 2023).
bone marrow failure syndrome (1 paper, 2018). "Altogether, our and previous observations highlight the importance of distinguishing patients with THPO mutations from those with MPL defects or other juvenile bone marrow failure syndromes." (PMID 29191945, 2018). "Very recently, two other homozygous THPO mutations (p.R99W and p.R157*) have been associated with inherited bone marrow failure syndrome in three unrelated pedigrees." (PMID 29191945, 2018).
cavernomas (1 paper, 2025). "Due to haemorrhagic complications of ITP at the age of 15 years presented with bleeding into cavernomas together with haematuria, romiplostim (fusion thrombopoietin peptide analogue) was administered." (PMID 41141376, 2025).